DLX2 (distal-less homeobox 2)
Diseases named in the same sentence as DLX2 in open-access papers (continued):
Sharing a sentence is not in itself a finding about the gene and the disease.
gastric cancer (continued). "Finally, we verified in vitro that DLX2 in gastric cancer cells can affect the expression of PDCD1 on the surface of T cells." (PMID 41244921, 2025). "In gastric cancer, high DLX2 expression has been detected in tumor tissues but not in adjacent normal tissues, and elevated DLX2 expression is associated with poor prognosis." (PMID 41244921, 2025). "The research results indicated that there exists a significant positive correlation between DLX2 and CTLA4, PDCD1, HAVCR2 and TIGIT, which may contribute to the gastric cancer cells’ ability to evade immune system attacks." (PMID 41244921, 2025). "Furthermore, we confirmed that the impact of DLX2 on the malignancy of gastric cancer can be reversed by PI3K/AKT inhibitors, indicating that DLX2 promotes the progression of gastric cancer malignancy through the PI3K/AKT pathway." (PMID 41244921, 2025).
glioblastoma (2 papers, 2021 to 2022). The most malignant astrocytic tumor (WHO grade IV). "In glioblastoma multiforme (GBM) patients, high levels of DLX2 have been associated with a poor survival outlook, and knockdown of DLX2 in GBM cells reduced cyclin D1 expression." (PMID 34203994, 2021).
Lung Squamous Cell Carcinoma (2 papers, 2022 to 2025). "Similar immunomodulatory roles of DLX2 have been reported in lung squamous cell carcinoma, and DLX2 was found to be associated with the IPS of PD-1/PD-L1 blockade as well as CTLA-4 combined with PD-1/PD-L1 blockade." (PMID 41244921, 2025).
melanoma (2 papers, 2016 to 2017). A malignant, usually aggressive tumor composed of atypical, neoplastic melanocytes. "This is also the case for zebrafish melanomas and human melanoma lines, which share super-enhancer signatures for the neural crest transcription factors Sox10 and Dlx2." (PMID 28894696, 2017). "On the other hand, DLX2 can also act as a negative feedback factor of TGF-β signaling and inhibit TGF-β-induced cell-cycle arrest and apoptosis increasing primary tumor growth and metastasis in B16 melanoma cells." (PMID 26799321, 2016).
osteosarcoma (2 papers, 2024 to 2025). A usually aggressive malignant bone-forming mesenchymal neoplasm, predominantly affecting adolescents and young adults. "In osteosarcoma, DLX2 has been shown to bind HOXC8 to repress CDH2 transcription, thereby promoting epithelial–mesenchymal transition (EMT)." (PMID 41244921, 2025). "DLX5 exerts oncogenic effects in osteosarcoma through NOTCH1 activation, and given that the Notch pathway drives TGF-β–induced EMT, DLX2 may contribute to EMT through similar mechanisms." (PMID 41244921, 2025).
Stroke (2 papers, 2011 to 2025). Sudden impairment of blood flow to a part of the brain due to occlusion or rupture of an artery to the brain. "The present study showed that stroke upregulated DLX2, which was concurrently with reduction of miR-124a, whereas miR-124a mimics reduced DLX2 expression in ischemic neural progenitor cells." (PMID 21887253, 2011). "Thus, downregulation of miR-124a by stroke could upregulate DLX2 expression, leading to proliferation of SVZ neural progenitor cells." (PMID 21887253, 2011).
acute myeloid leukemia (1 paper, 2019). Acute myeloid leukemia (AML) is a group of neoplasms arising from precursor cells committed to the myeloid cell-line differentiation. "Aberrant activities of particular NKL homeobox genes have been described in myeloid malignancies as well, exemplified by DLX2, HLX and VENTX in acute myeloid leukemia (AML)." (PMID 31825998, 2019).
atherosclerosis (1 paper, 2025). A disease characterized by the build-up of fatty material and calcium deposition in the arterial wall resulting in partial or complete occlusion of the arterial lumen. "After intersection analysis, three regulons (DLX2, HESX1, and KDM2A) were identified as master TRs in atherosclerosis." (PMID 40303308, 2025).
autoimmune disease (1 paper, 2022). A disorder resulting from loss of function or tissue destruction of an organ or multiple organs, arising from humoral or cellular immune responses of the individual to their own tissue constituents. "The results of function enrichment analysis showed that low-expression of DLX2 was closely related to various immune-related pathways like T/B/NK cell mediated immunity, interferon gamma/alpha response, and various autoimmune diseases." (PMID 36317140, 2022). "Low-expression DLX2 is related with various autoimmune disease (AID) like SLE and autoimmune thyroid disease as presented in KEGG functional enrichment analysis." (PMID 36317140, 2022). "Function enrichment analysis revealed that low-expression of DLX2 was closely related to various immune-related pathways like T/B/NK cell mediated immunity, interferon gamma/alpha response, and various autoimmune disease." (PMID 36317140, 2022).
autoimmune thyroid disease (1 paper, 2022). Inflammatory disease of the thyroid gland due to autoimmune responses leading to lymphocytic infiltration of the gland. "KEGG enrichment analysis revealed that DLX2-low group was associated with systemic lupus erythematosus (SLE), graft versus host disease, autoimmune thyroid disease, and other immune-related disease." (PMID 36317140, 2022).
brainstem infarction (1 paper, 2023). "Third, co-overexpression of BDNF and Dlx2 promoted the directional differentiation of the grafted NSCs into GABAergic neurons, the dominant subtype of neurons lost in brainstem infarction." (PMID 37365654, 2023).
breast tumors (1 paper, 2010). "In the present study we specifically investigated the involvement of DLX2 and DLX5/6 in breast tumor progression." (PMID 21108812, 2010). "In order to assess the role of DLX2 and DLX5 gene expression also in humans, we performed a preliminary analysis of the DLX status on 2 samples of normal breast tissue and on 2 samples of primary breast tumor." (PMID 21108812, 2010).
colon cancer (1 paper, 2011). "In colon cancer tissues, Dlx-2 expression varied; some colon cancer tissues had high levels of Dlx-2 mRNA, whereas others had Dlx-2 mRNA levels similar to or lower than those observed in normal tissue." (PMID 21917150, 2011). "In breast and colon cancers, Dlx-2 expression higher in tumor tissues than in matched non-tumorigenic tissues and stromal cells around cancer cells, i.e., fibroblasts and lymphocytes." (PMID 21917150, 2011).
keloid (1 paper, 2022). An irregularly shaped, elevated mark on the skin caused by deposits of excessive amounts of collagen during wound healing. "In terms of expression level, BMP4, MSX1, TBX2, SIX1, DLX5, and DLX2 were lowly expressed, while HAND2, IRX1, EDN1, and MEF2C were highly expressed in keloid fibroblasts." (PMID 35047146, 2022).
myelodysplastic syndrome (1 paper, 2021). A clonal hematopoietic disorder characterized by dysplasia and ineffective hematopoiesis in one or more of the hematopoietic cell lines. "Aberrant DLX gene expression has been shown for both DLX1 and DLX2 in T-ALL, AML and myelodysplastic syndrome (MDS) patients, showing divergent regulation in the malignant context." (PMID 34829904, 2021).
neuroblastoma (1 paper, 2020). Neuroblastoma (NB) is the most common solid, extracranial childhood tumor. "BMP2 induced neural differentiation in mouse neuroblastoma cells by increasing the expression of neurogenic transcription factors Dlx2, Brn3a, and NeuroD6." (PMID 32210188, 2020). "Our transcriptomic analysis did not support activation of DLX2, BRN3A, or NEUROD6 genes as being involved in the BMP4-induced phenotypes of neuroblastoma cells, as previously suggested by studies using BMP2." (PMID 32210188, 2020).
squamous cell carcinoma (1 paper, 2020). A carcinoma arising from squamous epithelial cells. "A downstream approach confirmed ID1, ID3 and DLX2 to be highly reproducibly down-regulated by milk in the squamous cell carcinoma cell line HSC2." (PMID 32246075, 2020).
teratocarcinoma (1 paper, 2017). A germ cell tumor characterized by the presence of an embryonal carcinoma component and a teratoma component. "Transfection of shDlx2#1 or #2 efficiently knocked down Dlx2 in P19 cells, a mouse teratocarcinoma cell line." (PMID 28276447, 2017).
tumor (26 papers, 2010 to 2025). "DLX2 is a homeobox transcription factor and its association with tumor progression and metastasis has been reported." (PMID 33924205, 2021). "GLS1 is known to be an important regulator of Snail-induced EMT and is also a metabolism-linked target gene of Dlx-2, contributing to tumor progression." (PMID 29636841, 2018). "We also demonstrate that Dlx-2 is implicated in metabolic stress-induced necrosis, suggesting a possible role(s) of Dlx-2 in tumor progression." (PMID 21917150, 2011). "Studies have demonstrated that DLX2 expression is associated with tumor invasion and metastasis." (PMID 41244921, 2025). "Our results suggest that Dlx-2 may be implicated in tumor progression via the regulation of metabolic stress-induced necrosis." (PMID 21917150, 2011). "Thus, Snail, Dlx-2, and Egr-1 seem to be implicated in GD-induced necrosis and tumor progression." (PMID 29636841, 2018). "Our analysis revealed that DLX2 expression was significantly greater in tumor tissues than in normal tissues." (PMID 41244921, 2025). "Our objectives were to establish DLX2 as an independent prognostic marker in GC, elucidate its role in modulating the tumor immune microenvironment, and define its mechanistic link with PI3K/AKT activation and EMT." (PMID 41244921, 2025). "This study demonstrated the role of DLX2 in promoting GC proliferation, migration, and invasion through in vitro functional assays and in vivo xenograft tumor models." (PMID 41244921, 2025). "Our findings revealed that elevated DLX2 expression is correlated with poor prognosis and enhanced tumor proliferation, migration, invasion, and immune evasion, positioning DLX2 as both a prognostic biomarker and a potential therapeutic target in GC." (PMID 41244921, 2025). "Functional assays and in vivo models evaluated the impact of DLX2 on tumor cell migration, invasion, and growth." (PMID 41244921, 2025). "Immune scoring analysis explored the relationship between DLX2 and the tumor immune microenvironment." (PMID 41244921, 2025). "This study validated the role of DLX2 in promoting GC proliferation, migration, and invasion through both in vitro functional assays and in vivo xenograft tumor models." (PMID 41244921, 2025). "Subsequently, CCK-8 assay showed that tumor cell viability was significantly decreased after DLX2 knockdown." (PMID 39717768, 2024). "Together, these results indicated that knockdown of DLX2 inhibited tumor cell activity, proliferation, migration, and invasion, thereby suppressing tumor growth." (PMID 39717768, 2024). "DLX2, a homeobox transcription factor, plays an indispensable role in tumor progression and metastasis in TGF-β-exposed cancer cells." (PMID 36686667, 2022). "DLX2-downregulated group was enriched in more immune-activating cells and lower tumor immune dysfunction and exclusion (TIDE) score." (PMID 36317140, 2022). "For example, lncRNA taurine upregulated gene 1 was found elevated expression in HCC and promotes tumor growth and metastasis by promoting distal-less homeobox 2 expression via sponging miR-216b-5p." (PMID 34484334, 2021). "The tumor tissues displayed an enriched expression of transcription factors (e.g., Dlx2, Gbx2, Foxb1, and Nkx2.2) critical for brain development, tanycyte markers (e.g., Ptprz1, Fabp7, Crym, and Gja1), and differentiation markers (e.g., Dcx, Olig1, and Cspg5)." (PMID 33863883, 2021). "High DLX-2 expression is an adverse factor for cancer prognosis, degree of tumor differentiation, histological grade, and metastasis in a variety of cancers." (PMID 34789836, 2021). "More importantly, TUG1 knockdown inhibited HCC tumor growth in vivo through upregulating miR-216b-5p via inactivation of the DLX2." (PMID 31920462, 2020).
tumor (continued). "High expression levels of Dlx-2 positively affect tumor size, depth of invasion, and metastasis stages in several cancers, including gastric adenocarcinoma and hepatocellular carcinoma." (PMID 30671168, 2018). "Snail and Dlx-2 contribute to tumor progression by promoting necrosis and inducing EMT and oncogenic metabolism." (PMID 29636841, 2018). "Accordingly, Snail and Dlx-2 contribute to tumor progression by promoting necrosis as well as by inducing EMT and oncogenic metabolism." (PMID 29636841, 2018). "Recently, we showed that distal-less homeobox-2 (Dlx-2), a homeodomain transcription factor involved in embryonic and tumor development, induces EMT and a glycolytic switch by increasing Snail expression." (PMID 26771232, 2016). "We previously showed that distal-less homeobox-2 (Dlx-2), a homeodomain transcription factor involved in embryonic and tumor development, induces glycolytic switch and epithelial-mesenchymal transition (EMT) by inducing Snail expression." (PMID 26771232, 2016). "Increased Dlx-2 expression was also detected in the inner regions, which experience metabolic stress, of human tumors and of a multicellular tumor spheroid, an in vitro model of solid tumors." (PMID 21917150, 2011). "It is noteworthy that strong positive Dlx-2 staining was observed in tumor cells adjacent to areas of necrosis and in the cells in the necrotic core." (PMID 21917150, 2011). "The high DLX2 expression group presented decreased immune and stromal scores, suggesting that DLX2 may play a crucial role in the tumor immune microenvironment by influencing immune evasion and stromal remodeling." (PMID 41244921, 2025). "We hypothesize that DLX2 is an independent prognostic marker and modulates the tumor immune microenvironment." (PMID 41244921, 2025). "Low DLX2 expression negatively correlates with immune activation–related pathways, suggesting that DLX2 may promote tumor immune evasion by suppressing the immune microenvironment." (PMID 41244921, 2025). "In GC, DLX2 is markedly upregulated in tumor versus normal tissues." (PMID 41244921, 2025). "Colony formation assay confirmed that DLX2 gene knockdown inhibited tumor cell aggregation." (PMID 39717768, 2024). "In addition, after DLX2 knockdown, the migratory and invasive abilities of tumor cells were assessed using the scratch and the transwell method, and the results showed that the levels of migration and invasion were significantly reduced." (PMID 39717768, 2024). "The results indicated that low-DLX2 expression was correlated with a more hot-tumor environment and might promote the activity of immunotherapy." (PMID 36317140, 2022). "Our study on an integrated bioinformatical analysis implied that DLX2 could be served as a promising indicator for remodeling tumor microenvironment status and predicting ICI response of patients with LUSC." (PMID 36317140, 2022). "Furthermore, the expression of TUG1, miR-216b-5p and DLX2 in resected tumor tissues was measured, compared to the sh-NC group, TUG1 and DLX2 were decreased and miR-216b-5p was increased in the sh-TUG1 group." (PMID 31920462, 2020). "In addition, Dlx-2 is involved in shifting from the TGF-β tumor suppressive activity in early stages to tumor promoting activity in later stages." (PMID 30671168, 2018). "Dlx-2 expression is induced by the metabolic stress-dependent induction of ROS and may contribute to tumor progression through the regulation of metabolic stress-induced necrosis." (PMID 30671168, 2018).
tumor (continued). "However, the role of DLX2 should be further confirmed in more in vitro studies with other human tumor cells as well as in animal studies to utilize the DLX2 as a therapeutic target for reducing metastatic ability and increasing radiosensitivity of tumors." (PMID 26799321, 2016). "According to recent reports, deregulation of DLX2 was found in human solid tumors and hematologic malignancies, and DLX2 is speculated to be involved in tumor progression via the regulation of metabolic stress-induced necrosis." (PMID 26799321, 2016). "We examined Dlx-2 protein expression using three-dimensional multicellular tumor spheroids (MTSs)." (PMID 21917150, 2011). "Immunoreactivity for Dlx-2 in the tumor cells was found exclusively in the nucleus." (PMID 21917150, 2011). "However, because Dlx-2 was also expressed throughout tumor tissues, its expression is likely to be regulated also by stimuli other than metabolic stress and plays an important role(s) in tumor development." (PMID 21917150, 2011). "We speculate that Dlx-2 may affect mitochondrial function and sensitize tumor cells to metabolic stress and death by necrosis." (PMID 21917150, 2011). "Thus, Dlx-2 expression was related to poor differentiation grade of tumor, indicating a role(s) of Dlx-2 in tumor development." (PMID 21917150, 2011). "Although these previous studies showed the potential role of DLX2 in the tumor progression and metastasis involving TGF-β signaling, the detailed biological role of DLX2 in the acquirement of CSC and EMT characteristics of irradiated cancer cells remains largely unknown." (PMID 33924205, 2021). "Moreover, Dlx2 also further supports tumour growth and metastasis." (PMID 33114183, 2020). "Above results indicated that TUG1 could promote tumor growth by miRNA-216b-5p/DLX2 in vivo." (PMID 31920462, 2020). "Thus, the Dlx-2/GLS1 cascade may promote tumor metastasis by increasing Snail-mediated anoikis resistance in addition to EMT." (PMID 26771232, 2016). "Therefore, the role of DLX2 in EMT process may differ with respect to the types of tumor cells and EMT stimuli." (PMID 26799321, 2016). "Also, DLX2 is speculated to be involved in tumor progression and aggressiveness by the regulation of metabolic stress-induced necrosis via the regulation of mitochondrial ROS." (PMID 26799321, 2016). "In conclusion, this study establishes DLX2 as a crucial regulator of GC malignancy, driving EMT and PI3K/AKT activation to fuel aggressive tumor phenotypes." (PMID 41244921, 2025). "In vitro and in vivo studies showed that DLX2 overexpression enhanced EMT, activated the PI3K/AKT pathway, and increased tumor cell migration and invasion." (PMID 41244921, 2025). "This study examines the role of DLX2 in GC progression, focusing on its activation of the PI3K/AKT pathway and induction of EMT, which promote tumor cell proliferation, migration, and anchorage-independent growth." (PMID 41244921, 2025). "We observed already statistically significant different accessibilities between healthy controls and COAD samples for TFs HNF4A and DLX2 and the other TFs, GRHL2, EVX2, LYL1, and PU.1 showed statistically significant differences at a 1% tumor level." (PMID 31604930, 2019). "Next, we compared accessibilities in subsamples with different tumor fractions for TFs selected based on our previous ATAC-seq and nucleosome plasma mapping, i.e., GRHL2, EVX2, DLX2, HNF4A, LYL1, and PU.1." (PMID 31604930, 2019). "In this study, we show that Dlx-2 induces EMT and regulates GLS1 expression and Gln metabolism, which increases tumor metastasis." (PMID 26771232, 2016).